CRABP1 (cellular retinoic acid binding protein 1)
Diseases named in the same sentence as CRABP1 in open-access papers (continued):
Sharing a sentence is not in itself a finding about the gene and the disease.
psoriasis (4 papers, 2019 to 2022). An autoimmune condition characterized by red, well-delineated plaques with silvery scales that are usually on the extensor surfaces and scalp. "It appeared that Crabp1 expression was dramatically and significantly reduced in multiple human inflammatory diseases including multiple sclerosis, lupus, inflammatory bowel diseases, vitiligo and psoriasis." (PMID 34193153, 2021).
skin tumor (4 papers, 2019 to 2025). "During the processes of developmental morphogenesis, adult hair follicle cycling, and skin tumor formation, CRABP1 and CRABP2 are dynamically regulated." (PMID 39457415, 2024). "We detected that CRABP1, Nestin, and Ephrin B2 are expressed in the intratumoural stroma as well as the tumour invasive front of skin tumours of appendages and BCCs." (PMID 31065284, 2019). "CRABP1 is expressed in the stroma of embryonic dermis and skin tumors but limited to the follicular dermal papilla of normal postnatal skin, which is upregulated in response to RA treatment or Notch activation and is negatively regulated by Wnt/β-catenin signaling." (PMID 41487473, 2025).
amyotrophic lateral sclerosis (3 papers, 2022 to 2023). Amyotrophic lateral sclerosis (ALS) is a neurodegenerative disease characterized by progressive muscular paralysis reflecting degeneration of motor neurons in the primary motor cortex, corticospinal tracts, brainstem and spinal cord. "Others’ studies have also shown that Crabp1 expression is reduced in MN disease models, such as spinal muscular atrophy and amyotrophic lateral sclerosis (ALS)." (PMID 38706516, 2023). "CRABP1 expression has been found to be reduced in the following neurodegenerative disease conditions: amyotrophic lateral sclerosis, spinal muscular dystrophy, and age-related macular degeneration." (PMID 35406141, 2022). "In MNs, CRABP1 protects against neuronal stress/death, and CKO mice spontaneously develop adult-onset progressive motor deterioration, mimicking amyotrophic lateral sclerosis (ALS) due to progressive MN death and neuromuscular junction defects." (PMID 36902410, 2023). "We have previously found that CRABP1 is highly expressed in spinal cord, specifically in spinal MNs, not in glia cells and reported that CKO mice, that lost CRABP1, spontaneously develop age-dependent, amyotrophic lateral sclerosis (ALS)-like motor degenerative disease." (PMID 38706516, 2023).
breast tumors (3 papers, 2014 to 2025). "CRABP1 has been associated with high regenerative competence in skin fibroblasts and is expressed in a subset of CAFs in breast tumors enriched for genes related to ECM deposition and remodeling." (PMID 40216939, 2025). "In contrast to CRABP1, the great majority of breast tumor tissues scored positive for CRABP2, with 90.7 % and 95.4 % of the scored samples showing cytoplasmic and nuclear CRABP2 immunoreactivity, respectively." (PMID 26142905, 2015). "Similar to a previous report indicating that CRABP1 is differentially expressed in different subtypes of pituitary adenomas, we found that CRABP1 is downregulated in ER+ breast tumors, but expressed in ER- and triple-negative tumors." (PMID 26142905, 2015). "Compared to normal mammary tissues, CRABP1 expression is significantly down-regulated in ER+ breast tumors, but maintained in triple-negative breast cancers." (PMID 26142905, 2015). "However, CRABP1 expression is maintained in ER/PR-negative breast tumors compared to normal mammary tissues." (PMID 26142905, 2015). "CRABP1 and CRABP2 expression in primary breast tumor tissues was analyzed using gene expression and tissue microarrays." (PMID 26142905, 2015).
clear cell ovarian adenocarcinoma (3 papers, 2015 to 2022). "The decreased expression of CRABP1 is associated with the poor prognosis of serous and clear cell ovarian adenocarcinoma." (PMID 36419120, 2022). "Reduced levels of CRABP1 are also associated with poorer prognosis in serous (n = 40) and clear cell ovarian adenocarcinoma (n = 59)." (PMID 26142905, 2015). "In serous ovarian adenocarcinomas and clear cell ovarian adenocarcinomas, reduced Crabp1 expression was tied to significantly poorer survival prognosis." (PMID 26935534, 2016).
follicular adenomas (3 papers, 2009 to 2018). "LCN2 and CRABP1 were also differentially expressed in DTC when compared with follicular thyroid adenoma." (PMID 29321030, 2018). "The strongest candidate genes which may be able to discriminate follicular adenomas and carcinomas, CRABP1, FABP4 and HMGA2, were validated in independent samples by qRT-PCR and immunohistochemistry." (PMID 29535811, 2018). "Gene expression of C1QL1 (a), LCN2 (b), CRABP1 (c) and CILP (d) genes was measured by real-time quantitative PCR in normal thyroid (NT) tissues, follicular thyroid adenoma (FTA) and differentiated thyroid cancer (DTC)." (PMID 29321030, 2018). "In all cases except one (CASP10, F-test, p<0.05), the gene expression level differentiated not only between macro- and micro-follicular adenomas but also between follicular adenomas and oncocytic adenomas, as in the case of CDH16 and CRABP1 genes." (PMID 19893615, 2009).
heart failure (3 papers, 2019 to 2025). Inability of the heart to pump blood at an adequate rate to meet tissue metabolic requirements. "We recently found that Crabp1 can also act as a signaling molecule to modulate calcium/calmodulin dependent protein kinase II in a mouse heart failure model where Crabp1 functions to protect against heart failure in the adult mice." (PMID 31358819, 2019). "In cardiomyocytes, CRABP1 protects cardiomyocytes from apoptosis triggered by adrenergic over-stimulation; therefore, Crabp1 knockout (CKO) mice are prone to isoproterenol-induced cardiomyopathy and heart failure." (PMID 36902410, 2023).
lymph node metastasis (3 papers, 2015 to 2023). "On the other hand, high levels of CRABP1 have been linked to lymph node metastasis and poor differentiation/high grade in pancreatic neuroendocrine tumors." (PMID 26142905, 2015). "High levels of CRABP1 have been detected in synovial sarcomas, lymph node metastasis, and pancreatic neuroendocrine tumors (pNETs)." (PMID 36673024, 2023).
Obesity (3 papers, 2022 to 2025). Accumulation of substantial excess body fat. "Finally, we suspected a correlation of CRABP1 with human diseases associated with obesity and/or inflammation." (PMID 35794192, 2022). "This suggests that CRABP1 probably plays a protective role against the development of obesity through, at least partially, regulating adipocytes and adipose tissue inflammation." (PMID 35794192, 2022). "Altogether, our data show that CRABP1 is beneficial in maintaining the health and function of adipocytes, which would protect against the development of obesity-related WAT inflammation, especially under an HFD feeding." (PMID 35794192, 2022). "For instance, CRABP1-expressing adipocytes may be locally delivered to adipose tissues to help correct the abnormally expanded obesity." (PMID 35406141, 2022).
thyroid cancer (3 papers, 2018 to 2025). "Notably, all the 10 thyroid cancer cell lines tested showed loss of CRABP1 expression." (PMID 29321030, 2018). "Loss of CRABP1 expression in thyroid cancer was shown in previous studies, and hypermethylation of CRABP1 promoter CpG islands has been shown as a possible explanation for its reduced expression in thyroid cancer and in other human cancers." (PMID 29321030, 2018). "Expression of CRABP1 was significantly lower in FTC, FVPTC and PTC and in all ten thyroid cancer cell lines than in normal thyroid and FTA." (PMID 29321030, 2018). "Gene expression values (normalized read counts) of C1QL1 (a), LCN2 (b), CRABP1 (c) and CILP (d) in differentiated thyroid cancer (DTC) and normal thyroid (NT) tissues available in The Cancer Genome Atlas (TCGA)." (PMID 29321030, 2018). "CRABP1 expression levels were successful measured by qPCR in 89 DTC (15 FTC, 19 FVPTC and 55 PTC), 10 thyroid cancer cell lines, 14 FTA, and 19 matched thyroid normal tissues." (PMID 29321030, 2018). "A regression model was performed with C1QL1, LCN2, CRABP1 and CILP expression values for thyroid cancer prognostic factors: age of patients (> 45 years), tumour size (> 4 cm), and presence of extrathyroidal extension of the tumour." (PMID 29321030, 2018).
Anxiety (2 papers, 2021 to 2025). Intense feelings of nervousness, tension, or panic often arise in response to interpersonal stresses. "It would be interesting to examine whether Crabp1 gene appears in the list of genes with disease association, such as for those patients suffering from anxiety or depression disorder." (PMID 34830120, 2021). "Among them, previous studies have shown that Crabp1 knockout (CKO) mice exhibited reduced anxiety-like behaviors accompanied by a lowered stress induced-corticosterone level." (PMID 39905509, 2025). "Crabp1 knockout (CKO) mice exhibit reduced anxiety-like behaviors accompanied by a lowered stress induced-corticosterone level." (PMID 34830120, 2021). "Using the Crabp1 gene knockout mouse model (CKO), we first observed significantly reduced acute stress-induced anxiety-like behaviors, accompanied by a much-lowered corticosterone level." (PMID 34830120, 2021). "In studying a Crabp1 knockout (CKO) mouse model, we first found that CKO mice exhibited reduced anxiety-like behaviors and a significantly lowered stress-induced corticosterone level following restraint stress." (PMID 34830120, 2021).
benign papillomas (2 papers, 2015 to 2019). "In previous studies, CRABP1 has been detected in murine papillomas and SCCs within the tumour stroma and at the junctions between the epidermal Keratin 14-positive cells and the dermis." (PMID 31065284, 2019). "Furthermore, they found that the CRABP1, CRABP2, and FABP5 proteins were overexpressed in both benign papillomas and malignant squamous cell carcinomas (SCCs)." (PMID 26503156, 2015).
colon adenocarcinoma (2 papers, 2017 to 2025). "We first compared the expression of five CRBPs—retinol‐binding protein 1 and 2 (RBP1/2), CRABP1, CRABP2, and FABP5—in normal (N) versus tumor (T) tissues in The Cancer Genome Atlas (TCGA)‐Colon Adenocarcinoma (COAD) dataset." (PMID 40305785, 2025).
depression (2 papers, 2021 to 2024). "This would suggest that the Crabp1 level might be lower in patients suffered from chronic stress (or depression)." (PMID 34830120, 2021).
esophageal squamous cell carcinoma (2 papers, 2015 to 2016). Esophageal squamous cell carcinoma (ESCC) is a type of esophageal carcinoma (EC) that can affect any part of the esophagus, but is usually located in the upper or middle third. "CRABP1 has been proposed to be a tumor suppressor in esophageal squamous cell carcinoma, with reduced CRABP1 levels associated with increased cell growth and distant lymph node metastasis." (PMID 26142905, 2015). "In esophageal squamous-cell carcinoma cells, absence of Crabp1 promoted cell growth." (PMID 26935534, 2016).
motor neuron disease (2 papers, 2020 to 2022). "The present study provides the evidence for the association of Shh-Gli1 regulation of Crabp1 expression with motor neuron differentiation, and that down-regulation of Crabp1, as well as the Shh-Gli signaling, is associated with motor neuron diseases in humans, such as ALS, SBMA, and SMA." (PMID 32527063, 2020). "This correlation strongly supports our proposition that Crabp1 up-regulation in motor neurons is physiologically relevant, and that dysregulation (specifically down-regulation) of this gene is strongly associated with motor neuron disease conditions." (PMID 32527063, 2020). "We then discuss an additional role of CRABP1 in regulating CaMKII activities, and its implication in heart and motor neuron diseases." (PMID 35406141, 2022). "The correlation of dysregulation in this gene with motor neuron diseases suggests certain physiological activity of CRABP1 in motor neurons." (PMID 32527063, 2020).
pancreatic ductal carcinoma (2 papers, 2016). "“(D) Compounds lose ability to induce ERK activity in human CRABP1 null cancer cell lines A2780 (ovarian) and KPC (pancreatic ductal carcinoma) after 100 nM, 30 min treatment (upper)." (PMID 27435798, 2016). "“(D) Compounds lose ability to induce ERK activity in human CRABP1 null cancer cell line A2780 (ovarian) and mouse KPC (pancreatic ductal carcinoma) after 100 nM, 30 min treatment (upper)." (PMID 27435798, 2016).
pituitary adenomas (2 papers, 2015 to 2021). "In AtT20, a pituitary gland adenoma cell line elevating or reducing Crabp1 level correspondingly increases or decreases FKBP5 expression, and its endogenous Crabp1 level is elevated by GR agonist dexamethasone or RA treatment." (PMID 34830120, 2021).
prostate carcinoma (2 papers, 2015 to 2019). A carcinoma that arises from epithelial cells of the prostate gland. "Therefore, in-depth molecular characterization of CRABP1 will be required for understanding of the molecular mechanism underlying the promotion of prostate cancer progression by CRABP1." (PMID 26124181, 2015). "Lentivirus-mediated overexpression of FLAG-CRABP1 increased cell proliferation as well as invasion in PC-3 cells, suggesting that CRABP1 can function as a positive regulator of prostate cancer progression." (PMID 26124181, 2015). "We then explored whether CRABP1 could regulate cell proliferation and invasion in prostate cancer cells." (PMID 26124181, 2015). "Although a few studies have shown that CRABP1 could promote cancer progression in some types of cancer, we now for the first time show that CRABP1 has cancer promoting property in prostate cancer cells." (PMID 26124181, 2015). "Moreover, it is known that CRABP1 is overexpressed in castration-resistant prostate cancer cells." (PMID 26124181, 2015). "However, it remains unknown how CRABP1 facilitates cell proliferation and invasion in prostate cancer cells." (PMID 26124181, 2015). "In this study, we identified CRABP1 as a novel CIC target, and provided a molecular basis of how CIC regulates prostate cancer progression." (PMID 26124181, 2015).
Rb (2 papers, 2022 to 2025). "The highest agreement between RNA and protein level was observed for DDB2, CHAF1B, and POLD1, which were upregulated in retinoblastoma, and RHO, PDE6A, and CRABP1, which were downregulated." (PMID 40395327, 2025).
schizophrenia (2 papers, 2024 to 2025). A major psychotic disorder characterized by abnormalities in the perception or expression of reality. "By our calculation, the regulation of CRABP1 by certain schizophrenia-associated TFs may constitute a crucial avenue through which it exerts its influence on schizophrenia." (PMID 39905509, 2025). "For example, TFs SMARCA1, TCF4, and TRPS1 have been confirmed to play crucial roles in schizophrenia, and they have been confirmed to target CRABP1." (PMID 39905509, 2025). "CRABP1 has also been recognized as a biomarker in defining schizophrenia organoids." (PMID 39905509, 2025). "For instance, TF-tagged genes CRABP1, DOK1, RBM28, and C12orf65 are regulated by multiple schizophrenia-related TFs." (PMID 39905509, 2025).
sebaceous carcinomas (2 papers, 2019 to 2022). "Dermal progenitors, such as cellular retinoic acid-binding protein 1 (CRABP1), were expressed at the tumor-stroma interaction site within the core of sebaceous carcinomas and CRABP1 and nestin expression was lower in sebaceous carcinoma than in benign sebaceous adenomas." (PMID 36439142, 2022). "Furthermore, CRABP1 was overexpressed in some areas within the sebaceous carcinomas of the eyelids." (PMID 31065284, 2019).
synovial sarcoma (2 papers, 2006 to 2023). "Additionally, many other genes that have been previously related to synovial sarcomas, such as the SSX4 gene, EGFR and SALL2, components of the retinoic acid pathway (CRABP1 and RARG) as well as retinoic acid induced genes (IRX5 and TGFβ2), were also included in this module." (PMID 16503973, 2006).
thyroid nodule (2 papers, 2009 to 2018). A small circumscribed mass in the THYROID GLAND that can be of neoplastic growth or non-neoplastic abnormality. "However, our results differed at the protein level compared to a study on cold thyroid nodules where both the expression of CRABP1 mRNA and the protein were downregulated compared to normal surrounding tissue." (PMID 19893615, 2009). "Our results suggest that CRABP1 should be tested in order to see if it may be used in FNAB, for the differential diagnosis of the thyroid nodules displaying morphological features suspicious of malignancy." (PMID 29321030, 2018).
viral infection (2 papers, 2024). "The expression of RA-regulated genes, such as RARA, RARB, CRABP1, HOXB1, and STRA6, were all downregulated after HSV-1 infection, thus further demonstrating that RA synthesis was inhibited by viral infection." (PMID 38989466, 2024).
basal cell carcinoma (1 paper, 2019). A carcinoma involving the basal cells. "In superficial basal cell carcinomas, we observed CRABP1-positive cells at the tumour-stroma interaction site, when the tumour was in the probes of the formation and early invasion." (PMID 31065284, 2019).
cardiac hypertrophy (1 paper, 2019). "These are supported by the fact that CRABP1 gene knockout (KO) mice exhibit multiple phenotypes including hippocampal NSC expansion and spontaneous cardiac hypertrophy." (PMID 31344789, 2019).
choriocarcinoma (1 paper, 2019). An aggressive malignant tumor arising from trophoblastic cells. "With the exception of CRABP1, the analysis of 23 CIMP regions revealed very little tumour-associated hypermethylation suggesting that CIMP may not be a universal phenomenon in gestational choriocarcinomas." (PMID 31357948, 2019).
COVID-19 (1 paper, 2024). A disease caused by infection with severe acute respiratory syndrome coronavirus 2. "CRABP1 was association with COVID-19 susceptibility (OR: 0.95, 95% CI: 0.91–0.99, P: 0.0290) using the IVW with a significance threshold (P < 5 × 10− 6)." (PMID 38671384, 2024). "CRABP1 was association with lower COVID-19 susceptibility (OR: 0.95, 95% CI: 0.91–0.99, P: 0.0290) using the IVW." (PMID 38671384, 2024). "We found evidence of possible causal association of retinol, RBP4, RDH16 and CRABP1 with the susceptibility, hospitalization and severity of COVID-19." (PMID 38671384, 2024). "Our study identified suggestive inverse associations for CRABP1 with COVID-19 susceptibility." (PMID 38671384, 2024). "We conducted a two-sample Mendelian randomization (MR) study to assess the associations of retinol, retinol binding protein 4 (RBP4), retinol dehydrogenase 16 (RDH16) and cellular retinoic acid binding protein 1 (CRABP1) with COVID-19 in European population." (PMID 38671384, 2024). "In the present study, based on the available GWAS, we investigate the causal effect of COVID-19 and retinol, RBP4, RDH16 and CRABP1 through two-sample MR approach." (PMID 38671384, 2024). "Here, we assessed the association between the development and severity of COVID-19, and retinol and RA signaling pathway, by MR, utilizing alleles as proxies for the genetically predicted circulating status of retinol, RBP4, RDH16 and CRABP1." (PMID 38671384, 2024).
embryonal carcinoma (1 paper, 2023). A non-seminomatous malignant germ cell tumor characterized by the presence of large germ cells with abundant cytoplasm resembling epithelial cells, geographic necrosis, high mitotic activity, and pseudoglandular and pseudopapillary structures formation. "We thus exploited the widely used P19 embryonal carcinoma cell line, which was shown to endogenously express both CRABP1 and CaMKII." (PMID 36902410, 2023).
endometrioid endometrial carcinoma (1 paper, 2021). "CRABP1 is a retinoic-acid-binding protein, the increased expression of which has already been associated with bad prognosis and increased proliferation in endometrioid endometrial carcinoma." (PMID 34503158, 2021).